BDNF (brain derived neurotrophic factor)
Diseases named in the same sentence as BDNF in open-access papers (continued):
Sharing a sentence is not in itself a finding about the gene and the disease.
diabetes (continued). "Our results showed that after induction of diabetes, FBS, and HbA1C increased, and serum insulin decreased significantly, but glycosylated albumin and serum BDNF did not change significantly." (PMID 32405353, 2020).
dementia (252 papers, 2008 to 2026). Loss of intellectual abilities interfering with an individual's social and occupational functions. "This is compatible with the physiological functions of the gene, given that the T allele of this variant appears to decrease BDNF levels and change dopaminergic transmissions and is a risk factor for dementia." (PMID 41007499, 2025). "The improvements reported were statistically significant, and when accompanied by physiological markers (e.g., increased BDNF), they suggest potential real-world benefits, including cognitive maintenance in old age or reduced risk of dementia." (PMID 41415845, 2025). "It’s fascinating to note that only women, applicants above the period of 80, and ones with academic backgrounds showed a significant correlation between plasma BDNF and the risk of Alzheimer’s and intrinsic dementia." (PMID 37287291, 2024). "Changes in BDNF protein expression are associated with the onset of neurodegenerative diseases, such as dementia." (PMID 38257270, 2024). "Roasted AM extract increased BDNF levels in HT22 cells, indicating prophylactic potential for neurodegenerative diseases associated with BDNF deficiency, such as dementia." (PMID 39594453, 2024). "As the BDNF level increases, the average time it takes for rats to find the hidden platform decreases, supporting the BDNF–dementia association in the literature." (PMID 39727960, 2024). "At the same time, higher serum BDNF levels in cognitively healthy adults lower the risk for dementia and AD." (PMID 39683869, 2024). "AD, which accounts for approximately 70% of dementia cases, causes dysfunction of the synapses as nerve cells die due to the deposition of β-amyloid (Aβ) and reduction in brain-derived neurotrophic factor (BDNF)." (PMID 38337492, 2024). "For example, higher time spent in MVPA has been associated with greater brain volume, circulating levels of brain-derived neurotrophic factor, and synaptic plasticity, ultimately resulting in improved cognitive function and reduced risk of dementia." (PMID 37197282, 2023). "Physical activity not only increases brain volume and levels of brain-derived neurotrophic factor, but also improves high blood pressure and elevated blood sugar levels, which are risk factors for dementia." (PMID 37600519, 2023). "Another study found that control participants with higher serum BDNF levels were at minimum risk of developing dementia and AD." (PMID 35625880, 2022). "We further show that cerebrospinal fluid LXA4 is reduced in patients with dementia and positively associated with cognitive performance, brain-derived neurotrophic factor (BDNF), and AD-linked amyloid-β." (PMID 36216800, 2022). "The presence of neurotoxic stimulus and coexisting neurological disorders causes an alteration in the level of BDNF and manifests into dementia and cognitive dysfunction." (PMID 35054805, 2022). "Serum BDNF levels are associated with the risk and severity of Alzheimer’s disease dementia, whereas BDNF Val66Met polymorphisms are associated with the phenotypic variability seen in patients with frontotemporal lobar degeneration (FTLD) syndromes." (PMID 35743271, 2022). "This study encouraged FHS researchers to explore in more detail the detailed association between BDNF in serum with the threat of dementia and AD." (PMID 35625880, 2022). "A positive association between BB-DNA and plasma BDNF levels was also found in AD patients, particularly those with more severe dementia (i.e., patients with CDR2)." (PMID 36613538, 2022). "This replicates and contributes to other studies that have shown that higher BDNF levels and increased Aβ ratio are indicative of a lower risk for dementia." (PMID 35822037, 2021). "Other types of dementia (frontotemporal, Lewy Body, or vascular) are associated with low BDNF levels, both in the systemic circulation and the central nervous system." (PMID 35008438, 2021).
dementia (continued). "Our results showed that changing lipid intake induced expression of BDNF in the hippocampus, since higher lipid intake is associated with dementia risks." (PMID 34796296, 2021). "The AUC analysis exhibited a good diagnostic performance of low BDNF in differentiation of HD cases from non-dementia controls, implying BDNF to be a potential biomarker of HD." (PMID 33631722, 2021). "It is, however, important to acknowledge that contradictory findings have also been reported with regard to the associations of BDNF Val66Met and risk for dementia." (PMID 32218234, 2020). "The current review examines the potential of the BDNF Val66Met variation to modulate an individual’s susceptibility and trajectory through cognitive changes associated with ageing and dementia." (PMID 32218234, 2020). "Increasing the level of stimulation of neuronal cell production through increased BDNF expression can reduce the risk of dementia and play a positive role in cognitive function." (PMID 32397675, 2020). "In humans, BDNF has been associated with psychiatric (e.g., schizophrenia, major depressive disorder, anxiety disorders) and neurological diseases (e.g., dementia, Huntington‘s disease)." (PMID 32326586, 2020). "By having BDNF levels higher by one standard deviation, the risk for AD or dementia was lowered by 33%." (PMID 30634650, 2019). "A recent study on the association between dementia treatment and serum BDNF found that treatment increased BDNF levels in persons with AD." (PMID 24670553, 2014). "We found that serum BDNF was associated with a number of characteristics which also associated with dementia, which suggests that future studies should control for these potential confounders." (PMID 24670553, 2014). "Moreover, BDNF association with dementia and cognitive functioning has been assessed on three different levels (methylation, expression, and genotype), while correcting for age and sex of participants." (PMID 41009553, 2025). "In blood samples of individuals with MCI and dementia, we have investigated DNA methylation of six regions in the BDNF gene, BDNF gene and protein expression, and association of BDNF Val66Met polymorphism with dementia and neurocognitive changes assessed by MMSE and CDT scales." (PMID 41009553, 2025). "Higher BDNF levels at baseline have been associated with decreased odds of developing dementia." (PMID 41153730, 2025). "These may include factors already associated with cognitive dysfunction and dementia in other populations, such as apolipoprotein E, complement receptor 1, clusterin, sortilin-related receptor 1, catechol-O-methyltransferase and BDNF." (PMID 40235626, 2025). "The literature suggests that decreased BDNF expression may be a risk factor for dementia and that dopaminergic transport changes may occur, with possible consequences arising in the reward and pleasure system." (PMID 41007499, 2025). "Therefore, to prevent AD, it is important to manage the pathological factors that cause dementia, and the pathological risk factors include Aβ and BDNF." (PMID 38337492, 2024). "BDNF levels, a protective factor against future occurrence of dementia and AD, implicated in neuronal and synaptic processes taking place in the neocortex and the hippocampus, were overall lower in the context of CI in PTSD, however this was independent of CI status." (PMID 38237700, 2024). "However, aging per se impairs BDNF levels, and aging has been identified as one of the main risk factors for the development of neurodegenerative diseases and dementias." (PMID 37108547, 2023). "Finally, we summarize studies supporting the possibility to use BDNF as an early biomarker in sensory and cognitive neurodegenerations such as hearing loss and dementia." (PMID 37109038, 2023).
dementia (continued). "On a more clinical note, drugs that could cause elevated BDNF levels, such as cerebrolysin, are instituted in the treatment of mild cognitive impairment, AD, and other types of dementia, often bringing notable clinical improvements." (PMID 36768132, 2023). "A higher serum BDNF level has also been linked to a reduced risk of dementia." (PMID 35090576, 2022). "Regular exercise reduces the risk of developing dementia and AD after the age of 65 which may be attributed to exercise-induced increases in BDNF and improved brain function, both of which influence cognitive functions positively." (PMID 35692417, 2022). "Additionally, BDNF has been linked to the syndromes associated with neurodegenerative diseases such as dementia and MCI." (PMID 35743271, 2022). "Even though BDNF levels measured from neural tissue is a more reliable indicator of this brain-enriched pathway, serum BDNF levels in humans have also been shown to partly mediate the association between levels of social support and dementia risk." (PMID 34299756, 2021). "In particular, an increase in BDNF, which may improve dementia risk factors through enhanced functional fitness, is reported to reduce B-amyloid frequently found in the brain of Alzheimer’s patients." (PMID 34360254, 2021). "Given that Croatian veterans with PTSD are now middle-aged men, and the association between PTSD and all-cause dementia, the assessment of BDNF polymorphisms may have a role in establishing which patients may be at particular risk for cognitive deterioration." (PMID 33926045, 2021). "Together, these findings show that global DNA methylation represents the biomarker with less diagnostic power than SIRT activity and BDNF expression for diagnosing and monitoring disease activity and treatment intervention in patients with dementia than in individuals with PD." (PMID 35008438, 2021). "Given that smoking increases dementia risk, BDNF rs56164415 polymorphism may have moderating or additive effects, which deserves future studies." (PMID 33926045, 2021). "However, in the healthy aging and AD stages, BDNF likely serves a neuroprotective role and thus associates with better cognition, with higher peripheral BDNF levels protecting the older adults against dementia." (PMID 34607976, 2021). "A few studies have demonstrated that serum BDNF levels are associated with incident dementia, but there is a dearth of literature examining the co-morbid associations between intestinal barrier integrity and serum BDNF and if they are associated with AD dementia in older adults." (PMID 33661922, 2021). "The aim of this review was to examine the potential of the BDNF Val66Met polymorphism to alter an individual’s susceptibility to brain ageing and dementia and to further identify pathways through which these effects may be conferred." (PMID 32218234, 2020). "Therefore, the decrease in BDNF concentration is considered a biological indicator for memory and general cognitive impairment caused by dementia." (PMID 32397675, 2020). "Higher levels of serum brain-derived neurotrophic factor (involved, among other functions, in synaptogenesis) have been suggested to play a mediating role between emotional support gained through social engagement and risk of dementia." (PMID 33192732, 2020). "In conclusion, we suggest that physical inactivity, hippocampal atrophy and hypofunction of BDNF signaling individually associate with age-related memory dysfunction and they might all be targets to prevent dementia." (PMID 33020545, 2020). "However, others have found the BDNF genotype does play a role in the cognitive performance of individuals at higher risk of developing dementia." (PMID 32218234, 2020). "Interestingly, subsequent subgroup analysis in this investigation showed that the association of high BDNF levels and lower risk of dementia was found solely in women with a college degree." (PMID 32218234, 2020).
dementia (continued). "These prospective studies could provide the foundation for the usage of BDNF in combination with other biomarkers in the predictive, diagnostic, and treatment response context-of-use in AD and dementia." (PMID 30634650, 2019). "Higher levels of BDNF (brain-derived neurotrophic factor), which has been shown to improve synaptic plasticity and long-term memory, may decrease the risk of dementia." (PMID 30096932, 2018). "Preclinical findings are paralleled by evidence in human studies that indicate that high serum levels of mBDNF, as well as high BDNF gene expression, are associated with a reduced risk of dementia in elderly subjects and a milder disease course in dementia patients." (PMID 29950603, 2018). "Taken together, human studies suggested that a loss of BDNF may lead to vulnerability to dementia due to neurodegeneration, emphasizing the importance of BDNF as a potential pharmacological target." (PMID 29249935, 2017). "The levels of BDNF in serum are also associated with the severity of dementia." (PMID 28377712, 2017). "Moreover, our results do confirm BDNF’s and cortisol’s reported associations with dementia severity, and we can also confirm both testosterone’s lack of an association with the GDS30 and its significant association with dementia." (PMID 28594820, 2017). "An up-regulation of BDNF would therefore be beneficial, and maybe act as a protecting factor against dementia and other memory deficiencies." (PMID 26379621, 2015). "For example, BDNF might be implicated in the increased vulnerability to dementia in post-menopausal women." (PMID 21247257, 2012). "Furthermore, in dementia patients, lower BDNF serum levels have been associated with a higher risk of neurodegenerative processes, which is in line with the neuroprotective effects of BDNF." (PMID 21247257, 2012). "Additionally, longitudinal designs are needed to determine whether increases in BDNF may be associated with longer retention of cognitive improvements or predict slower progression toward dementia." (PMID 41153730, 2025). "Thus, the involvement of BDNF in dementias suggests that the BDNF pathway may be linked to neurodegeneration." (PMID 41516057, 2025). "However, the value of BNDF methylation as an early biomarker for dementia was questioned by a later study by Fransquet and collaborators, who investigated the association between peripheral blood and buccal BDNF gene methylation and incidence of all-cause dementia after a 14-year follow-up." (PMID 35893045, 2022). "Indeed, lower BDNF levels have been associated with lower cognitive performance, and patients with lower BDNF levels have been found to be at greater risk of progressing toward dementia." (PMID 34557534, 2021). "Higher serum BDNF levels have been suggested to protect against dementia occurrence, therefore they may represent an important mediator of the beneficial effects of cognitively stimulating activities on cognitive reserve and dementia risk." (PMID 34408648, 2021). "Disrupted serum BDNF may correlate also with the elevated risk of dementia in DS individuals." (PMID 32280719, 2020). "On balance, research to date indicates that the BDNF Met allele at this codon is potentially associated with a detrimental influence on the level of cognitive functioning in older adults and may also impart increased risk of progression to dementia." (PMID 32218234, 2020). "Interestingly, nicotine use has been linked to a decreased risk of dementia, which might point to a mediating role for BDNF." (PMID 21247257, 2012). "However, the striking drop in peripheral BDNF levels with age might predispose these patients to clinical manifestations of dementia in later life." (PMID 20181009, 2010). "This pilot study demonstrates the feasibility of combining exergaming with noninvasive saliva collection and ddPCR to examine BDNF promoter IV methylation in older adults with dementia or LLD." (PMID 41146751, 2025).
dementia (continued). "Vitamin D modulates neurotrophic factors such as Brain-Derived Neurotrophic Factor (BDNF) and demonstrates neuroprotective properties, with low levels associated with dementia risk." (PMID 40806128, 2025). "Some studies indicated transiently elevated BDNF levels in early stages of dementia, probably due to compensatory or repair mechanisms." (PMID 41009553, 2025). "This study investigated differences in the distribution of BDNF Val66Met (rs6265) variants, as well as in peripheral BDNF DNA methylation, gene expression, and protein levels, between persons with MCI and dementia." (PMID 41009553, 2025). "Individual CpGs in tested BDNF amplicons have also shown modest differences in methylation between dementia and MCI groups." (PMID 41009553, 2025). "It presents an innovative integration of exergaming with noninvasive saliva collection and ddPCR analysis of the BDNF gene at promoter IV sites -39 and -35, offering a novel approach to examine neuroplasticity biomarkers in older adults with dementia or LLD." (PMID 41146751, 2025). "Hierarchical logistic regression was used to test the effect of age and sex as predictors of dementia, in addition to 6 tested BDNF amplicons." (PMID 41009553, 2025). "An insignificant decline in BDNF mRNA levels in dementia patients positively correlated with significantly lower BDNF plasma levels, especially pronounced in severe dementia patients." (PMID 41009553, 2025). "The 2015 study in Stem Cell Reports used neural stem cells (NSCs) overexpressing BDNF in a model of dementia with Lewy bodies." (PMID 40656325, 2025). "For example, in a scopolamine-induced dementia model, Stachys extract helped prevent memory decline, accompanied by elevated brain-derived neurotrophic factor (BDNF) levels and enhanced cholinergic system activity." (PMID 40282224, 2025). "This present study also observed the trend for lower expression of peripheral BDNF mRNA and significantly lower BDNF plasma levels in patients with dementia, especially severe dementia." (PMID 41009553, 2025). "A subset of individuals with MCI and dementia was chosen for relative quantification of BDNF gene expression, while BDNF protein expression was analyzed in all participants." (PMID 41009553, 2025). "Further studies should evaluate the translational potential of these peripheral BDNF-based biomarkers for dementia." (PMID 41009553, 2025). "Dementia patients had lower peripheral BDNF gene expression in comparison to the MCI group, although this result was not significant (U = 1994.5; p = 0.716)." (PMID 41009553, 2025). "Apart from dementia and AD, the salient components influencing the transmission of BDNF concentrations within the system are nutritional restrictions and other bodily moments." (PMID 37287291, 2024). "Therapeutic applications aim to amplify low levels of BDNF in the plasma from normal people and those who are eventually prone to develop dementia or Alzheimer’s." (PMID 37287291, 2024). "Finally, these findings suggest that loss of BDNF that occurs downstream of abnormal increases in Aβ may increase vulnerability to neuronal dysfunction via tau and precipitate accelerated clinical disease progression in pre-dementia stages of AD." (PMID 38454193, 2024). "It has been repetitively demonstrated that BDNF levels in the CNS and the periphery are altered during pathological conditions characterized by cognitive dysfunctions and dementia." (PMID 38386354, 2024). "As a non-pharmacological treatment, YPT can improve the expression of miR-134a and SIRT-1, CREB, and BDNF proteins as much as or more than estrogen therapy, ameliorating AD-induced dementia in aged OVX rats." (PMID 39061398, 2024). "The administration of plant extracts to animals exhibiting dementia reversed Sco-induced changes in brain BDNF and pCREB concentrations." (PMID 38339117, 2024). "They observed that those with extremely high serum BDNF values are least prone to develop Alzheimer’s and dementia." (PMID 37287291, 2024).